LMNB1 (lamin B1)
Diseases named in the same sentence as LMNB1 in open-access papers (continued):
Sharing a sentence is not in itself a finding about the gene and the disease.
tumor (61 papers, 2009 to 2025). "It functions as a tumor suppressor because loss of Lamin B1 is associated with enrichment of genes involved in EMT, growth and migration." (PMID 41310103, 2025). "In HCC, overexpression of LMNB1 has been associated with advanced pathological staging, poor prognosis, and increased tumor aggressiveness." (PMID 40315269, 2025). "We found that white matter associated invasive tumor cells had low expression of lamin A/C but expressed lamin B1/B220." (PMID 38195678, 2024). "Of note, cleavage of histone H3 and loss of lamin B1 also occur during cellular senescence, a process known to limit tumor progression." (PMID 36752151, 2023). "Misregulation of lamins are often associated with tumor aggressiveness and metastasis, and this alteration of lamin level, especially increased level of Lamin B1, has been suggested as a biomarker and even as a therapeutical target." (PMID 33918867, 2021). "Dysregulated expression of LMNB1 was also associated with several types of neoplastic diseases and patient survival." (PMID 32471220, 2020). "We show that silencing of lamin B1 or loss of a single lamin B1 allele is sufficient to induce or greatly promote tumor formation." (PMID 31015297, 2019). "Similar results were achieved by Sunet al.18, who used proteomic analysis to demonstrate that overexpression of lamin B1 was significantly associated with an increased number of tumor nodules and the size of tumors." (PMID 30467522, 2018). "Loss of lamin B1 levels have been associated with cellular senescence, a potent tumor-suppressive mechanism that leads to an irreversible cell cycle exit, and the lamin B1 loss has also been suggested as a senescence-associated biomarker." (PMID 29580221, 2018). "The dysregulation of LMNB1 is associated with tumor progression." (PMID 35436411, 2022). "Since CD4+ Th2 cells and Th2 cytokines such as interleukin-4 (IL-4), IL-5, IL-6, IL10 and IL13 were thought to be associated with immunosuppressive contexture and tumor-promoting effects, we believed that LMNB1 could be considered as a biomarker of immunosuppressive microenvironment." (PMID 35241075, 2022). "Emerging evidence suggests that LMNB1 also contributes to tumor immune evasion by regulating immune balance within the tumor microenvironment." (PMID 40315269, 2025). "This led to cleavage of histone H3 and lamin B1 and extensive nuclear remodeling, ultimately leading to reduced tumor growth." (PMID 36752151, 2023). "LMNB1 has been identified as a tumor promoter in LUAD; it inhibits LUAD cell proliferation by inducing DNA damage and cell senescence." (PMID 37266661, 2023). "Depletion of lamin B1 slowed the tumor growth of A549 cells concomitant with decreased phosphorylation of AKT." (PMID 38067205, 2023). "Functionally, increased expression of LMNB1 in AsPC‐1 cells promoted cell migration, invasion, proliferation, and reversed the anti‐tumor effects of si‐circPTPRA#1." (PMID 37041721, 2023). "In vivo data confirmed that tumor weight and volume were significantly increased by overexpression of circPTPRA, but sh‐LMNB1 partially rescued those phenotypes." (PMID 37041721, 2023). "We utilized the matched tumor samples in our cohort that exhibited a decline in NOXA protein expression post-NAC (n = 41) to investigate whether there is an association with the induction of TIS as determined by the decrease in Lamin B1 and Ki-67 accompanied by the increase of p16INK4a." (PMID 37741850, 2023). "Firstly, we detected LMNB1 mRNA expression in 25 pairs of KIRC tumor tissues and adjacent normal tissues by qRT-PCR." (PMID 35241075, 2022). "It has been reported that LMNB1 is involved in BPs, such as the proliferation and migration of various tumor cells." (PMID 36277723, 2022).
tumor (continued). "Pathway enrichment analysis was carried out to explore the possible mechanism of LMNB1 on tumorigenesis and tumor progression." (PMID 35241075, 2022). "LMNB1 has been identified in several studies searching for tumor biomarkers, many of which have demonstrated that it plays a vital role in carcinogenesi." (PMID 36005596, 2022). "In our study, KEGG enrichment analysis using LMNB1-related partners based on TCGA datasets indicated that “cell cycle” and “DNA replication” are concerned in the effects of LMNB1 on tumor pathogenesis." (PMID 35241075, 2022). "Further research based on multicenter design and relatively large sample size will help to draw a solid conclusion of LMNB1 expression in tumor tissues." (PMID 35241075, 2022). "As expected, we found that the tumor epithelial areas in the PRAD specimens displaying strong staining of lamin B1 also had heavy signals of BRCA1." (PMID 35241075, 2022). "Among the normal breast epithelium samples (Group A), lamin B1 mean positive protein expression was 93% (range: 80–95%), while all the 50 adjacent non-tumor samples had a score of 95% lamin B1 positive staining." (PMID 35328162, 2022). "According to bioinformatics analysis, LMNB1 is substantially abundant in LUAD tissues and is associated with tumor stage and patient survival (P < 0.05)." (PMID 35712471, 2022). "Our analysis revealed that LMNB1 was upregulated in HCC and that increased LMNB1 expression was positively correlated with advanced TNM stage, worse histological grade, high risk of tumor metastasis and dismal prognosis." (PMID 35436411, 2022). "The expression of p21CIP1, H3K9Me3, and Lamin B1 was immunohistochemically determined in paraffin-embedded tumor samples obtained intraoperatively following the completion of NAC treatment and scoring for these markers was performed." (PMID 33948615, 2021). "The tumours expressed lower levels of lamin B1 (a Dp71-binding partner), matrix metalloproteinase 2 (MMP-2) and B cell lymphoma 2 (Bcl-2), which the authors linked to the reduced malignancy in this model." (PMID 33188621, 2021). "Immunoreactivity of p21CIP1, H3K9Me3, Lamin B1 was localized in the nuclei of tumor cells in consistence with their typical expression (SupplementaryFigure S2)." (PMID 33948615, 2021). "Our analysis showed that the expression of p21CIP1, H3K9Me3, and Lamin B1 in tumor samples of patients who developed partial or incomplete response to NAC was 94.6, 75.7, and 48.6%, respectively." (PMID 33948615, 2021). "Epithelial–mesenchymal transition, tumor growth, cell migration and metastasis is promoted by lamin B1 silencing in lung epithelial cells." (PMID 32321983, 2020). "Lamin B1 silencing in lung epithelial cells promoted epithelial–mesenchymal transition, cell migration, tumor growth, and metastasis." (PMID 31015297, 2019). "Consistent with this, silencing of RET dramatically reduced the highly elevated tumor growth and metastatic ability of lamin B1–depleted cells." (PMID 31015297, 2019). "To further examine the role of lamin B1 downregulation in tumor growth and metastatic dissemination in vivo, we injected control and lamin B1 KD MLE12 cells intravenously in nude mice." (PMID 31015297, 2019). "The study also aimed to reveal the correlation between lamin B1 mRNA levels with the tumor size and the number of tumor nodules, represented using the Barcelona-Clinic Liver Cancer (BCLC) Staging System12, as well as to serum AFP level." (PMID 30467522, 2018). "In an attempt to study the prognostic significance of lamin B1, lamin B1 mRNA plasma levels (2-ΔΔCq) was compared between patients with one tumor nodule and those with two or more nodules." (PMID 30467522, 2018). "On applying conventional RT-PCR, (not real time PCR) there was an increase in the positivity rate of circulating lamin B1 mRNA that gradually increased with tumor stage progression." (PMID 30467522, 2018).
tumor (continued). "Immunohistochemical analysis revealed that SAβ-gal positivity inversely correlated with Lamin B1 expression in these samples, supporting the notion that SAβ-gal-positive tumor cells are indeed in the senescent state." (PMID 27713152, 2016). "Increasing lamin B1 expression results in the growth inhibition of SGC7901, which suggests that Dp71-lamin B1 protein complex plays an important role for the newly identified tumor suppressive function of Dp71." (PMID 27449096, 2016). "Some progress has also been made in the clinical application of LMNB1, and the findings indicate that LMNB1 could become a new tumor marker and therapeutic target." (PMID 38824174, 2024). "The authors suggested that there is a potential link between LMNB1 with the early stages of PCa progression, but the malignant potential of tumor-initiating cells may require additional molecular changes to be explained." (PMID 38824174, 2024). "In addition, LMNB1 also plays an important role in tumor progression, and the biological function of LMNB1 is closely related to the abnormal proliferation and potential tumorigenicity of tumor cells." (PMID 37041721, 2023). "Furthermore, IHC established that after the knockdown of LMNB1, the protein levels of Ki-67 and LMNB1 in tumor tissues were considerably down-regulated." (PMID 35712471, 2022). "All these findings demonstrated that LMNB1 may act as a tumor promoter and prognostic marker for HCC." (PMID 35436411, 2022). "To learn more about the involvement of LMNB1 in tumorigenesis and proliferation in vivo, we injected shcontrol A549 cells and shLMNB1 A549 cells subcutaneously, respectively, for establishing a xenograft tumor model in tumor-bearing mice." (PMID 35712471, 2022). "In addition to transcriptome analysis, we further compared the protein level of lamin B1 in different tumor kinds through UALCAN resource which provides protein expression analysis using data from CPTAC." (PMID 35241075, 2022). "In addition, TIMER2.0 assisted us to show the detail of the correlation between LMNB1 and every single gene in the PROfound signature across all TCGA tumor kinds." (PMID 35241075, 2022). "With the aid of TIMER2.0 resource, we employed the EPIC, TIMER, QUANTISEQ, XCELL, CIBERSORT, CIBERSORT-ABS methods to analyze the correlation between the infiltration levels of CD4+ T cell subtypes and the mRNA expression of LMNB1 across different TCGA tumor kinds." (PMID 35241075, 2022). "Overall, we hold the opinion that LMNB1 played an important role in tumor growth and cell mitosis." (PMID 35241075, 2022). "At the same time, in vivo mouse xenograft experiments showed that the tumor volume of the LMNB1-silenced group was significantly reduced, compared to that of the control group (P < 0.01), and the proliferation biomarker Ki-67 level (P < 0.01) was considerably reduced." (PMID 35712471, 2022). "This is also probably exacerbated by the lower LMNB1 levels in tumors and may be affected by tumor type or stage, or tumor zone, between which lamin levels can vary." (PMID 35681541, 2022). "The gene expression level and potential oncogenic roles of LMNB1 in The Cancer Genome Atlas (TCGA) database were analyzed with Tumor Immune Estimation Resource version 2 (TIMER2.0), Gene Expression Profiling Interactive Analysis version 2 (GEPIA2), UALCAN and Sangerbox tools." (PMID 35241075, 2022). "Furthermore, western blotting and IHC staining confirmed that lamin B1 protein level in tumor specimens was much higher than the corresponding normal tissues." (PMID 35241075, 2022). "LMNB1 promotes tumor progression through multiple mechanisms." (PMID 35436411, 2022). "Numerous studies have demonstrated the expression of lamin B1 in other malignant tumor tissue." (PMID 35328162, 2022).
tumor (continued). "Compared to normal tissues, LMNB1 was significantly upregulated in most types of tumor tissues." (PMID 35436411, 2022). "The role of LMNB1 in tumor initiation and progression still remain elusive." (PMID 35241075, 2022). "Among tumor cells, 143B cells showed the lowest amount of lamin B1." (PMID 32069980, 2020). "RET depletion in control and lamin B1 KD cells resulted in a significant decrease in tumor volume." (PMID 31015297, 2019). "Furthermore, we found a significantly increased number of tumor nodules with a large volume in C57BL/6 mice injected intravenously with lamin B1–silenced LLC1 cells compared with controls." (PMID 31015297, 2019). "Similarly there was a significant difference in lamin B1 expression in patients with tumor sizes ≤3 cm versus those with tumors >3 cm, with median (Q1–Q3) values of 2.0 (1.7–2.4) and 10.9 (5.1–22.3), respectively." (PMID 30467522, 2018). "In addition, mouse tumor formation experiments confirmed the effect of LMNB1 on tumor growth." (PMID 35712471, 2022). "Therefore, development of new strategies targeting LMNB1 or Th2 cells may help to redress Th1/Th2 imbalance and improve the prognosis of tumor patients with high LMNB1 expression." (PMID 35241075, 2022). "Moreover, provided that an analogous mechanism of 53BP1 modulation is mediated by lamin B1 in bone or epithelial tumour cells, it should be interesting to investigate whether different lamin platforms anchor 53BP1 in transformed cells." (PMID 36467410, 2022). "However, expression level of Lamin B1 is significantly correlated with tumor grade." (PMID 33948615, 2021). "Interestingly, LMNB1, RACGAP1, TK1, and ZWINT were all positively associated with tumor purity." (PMID 31306099, 2019). "Importantly, we found a much higher number of spontaneous metastases with larger tumor volume in the lungs of mice injected with lamin B1–depleted LLC1 cells compared with controls, whereas almost no metastasis was observed in mice injected with RET KD and lamin B1/RET KD LLC1 cells." (PMID 31015297, 2019). "In the 3 cases where the proteomes of tumor cells freshly prepared from tumor nodules could be tested with autologous sera, two antigens, lamin B1 and vimentin, were detected with two of the tumor-serum combinations with otherwise heterogeneous antigenicity patterns." (PMID 20020065, 2009). "LC3B was shown to specifically interact with lamin B1 in RAS-activated fibroblasts as a gateway to induce senescence and as a tumor suppressor mechanism." (PMID 40397664, 2025). "The transcriptome analysis showed that the COAD tumors had more lamin transcripts than normal tissue, supporting the upregulation of LMNA, LMNB1, and LMNB2 expressions in tumor tissues." (PMID 40708945, 2025). "During the aging process induced by etoposide, LMNB1 expression decreased, leading to a significant decrease in the proliferation rate of AKI-2, 786-O, and 769-P tumor cell lines." (PMID 38824174, 2024). "On the other hand, decreased expression of LMNB1 in PANC‐1 cells significantly inhibited cell migration, invasion, proliferation, and blocked the pro‐tumor effects induced by OE‐circPTPRA." (PMID 37041721, 2023). "LMNB1 knockdown in lung epithelial cells promoted EMT, cell migration, tumor growth, and metastasis by activating RET/p38 signaling." (PMID 36011023, 2022). "Moreover, the results of functional annotation analysis were concentrated on tumor metastasis-related biological processes, including epithelial-mesenchymal transition, focal adhesion, extracellular matrix, cell junctions and cell adhesion, reinforcing the idea that LMNB1 promotes HCC metastasis." (PMID 35436411, 2022). "These previous findings were consistent with our study, emphasizing that LMNB1 and LMNB2 play important roles in tumor progression." (PMID 36405011, 2022). "In this study, we first demonstrated a statistical positive correlation between the mRNA expression of LMNB1 and the infiltration level of CD4+ Th2 cells in all the TCGA tumor types excluding UCS." (PMID 35241075, 2022).
tumor (continued). "Lamin B1 depletion results in profound changes in the H3K27me3 landscape and promotes EMT, cell migration, tumor growth, and metastasis." (PMID 31015297, 2019). "Having suggested a functional involvement of Lamin B1 in SHM regulation and tumour progression, there is a number of questions that are still outstanding and warrant further investigation." (PMID 28804121, 2018). "This up-regulation expands to other potential tumor markers including A1AT1, tropomyosin-4, TUBB3, ACTN4, DDX3X, LMNB1, PARP and vimentin." (PMID 29109428, 2017). "Lamin B1-pcDNA3.1 plasmid was constructed and transfected into SGC7901 cells to verify its tumor suppression function." (PMID 27449096, 2016). "Western blot results showed that S1PR1, cyclin B1, PDK1, and lamin B1 protein levels were significantly decreased, whereas P21, P62, histone H3, IGFBP7, and PAI-1 protein levels were significantly increased in S1PR1 knockout tumor tissue." (PMID 37828220, 2023). "On the other hand, our analysis suggested that expression level of Lamin B1 is significantly correlated with tumor grade, but not significantly correlated with pathologic TNM stage or receptor status." (PMID 33948615, 2021). "The expression of LMNB1, TK1, ZWINT, and RACGAP1 was positively associated with tumor purity, while no or weak associations were observed for hub genes and infiltrating immune cells in PCa tissue samples." (PMID 31306099, 2019). "Lamin B1–depleted MLE12 showed markedly increased anchorage independent growth, one of the hallmarks of malignant transformation, and dramatically increased tumor growth in vivo." (PMID 31015297, 2019). "Finally, taking into account clear involvement of Lamin B1 in the pathophysiology of GC and post-GC B-cell malignancies, manipulating nuclear Lamin B1 levels could provide a novel therapeutic approach to these tumours, beyond the treatment modalities based on chemotherapy or monoclonal antibodies." (PMID 28804121, 2018). "Moreover, comparison between HCC patients with tumor size >3 cm revealed a significantly higher values versus those with tumor size ≤3 cm as regards AFP and lamin B1 (Z=3.1, p<0.01 and Z=4.6, p<0.001), respectively." (PMID 30467522, 2018). "Furthermore, LMNB1 has been identified as a clinically useful biomarker for early-stage HCC in both tumor tissues and plasma, with its expression levels positively correlating with tumor stage." (PMID 40315269, 2025). "Moreover, we observed a slight increase in the number of tumor samples that were not exposed to NAC that showed higher lamin B1 protein expression when there was positive lymphovascular invasion, albeit not statistically significant (p value = 0.565)." (PMID 35328162, 2022). "Interestingly, the authors showed that upregulation of lamin B1 alters 53BP1 recruitment to DNA damage foci by strengthening lamin B1-53BP1 complexes, while that mechanism does not involve lamin A, at least in tumour cells." (PMID 36467410, 2022). "Moreover, enhanced LMNB1 expression was found to be closely correlated with advanced TNM stage, poorer histological differentiation, higher levels of AFP, tumor recurrence and tumor metastasis." (PMID 35436411, 2022). "In addition, we characterized the protein expression level of lamin B1 in the adjacent non-malignant tissue of group B. Group B is comprised of 87 tumor samples that were not exposed to NAC." (PMID 35328162, 2022). "Thus, lamin B1 depletion promotes EMT, tumor growth, and metastasis." (PMID 31015297, 2019). "Lamin B1 and AFP could both differentiate HCC patients with one tumor nodule (T1) from those with two or more tumor nodules (T2&Tm), as well as between those with tumor sizes >3 cm and ≤3 cm." (PMID 30467522, 2018). "Notably, normal luminal cells showed high expression of Lamin B1, whereas adjacent tumor cells expressed low or no Lamin B1." (PMID 27713152, 2016).